LGALS8 (galectin 8)
Diseases named in the same sentence as LGALS8 in open-access papers (continued):
Sharing a sentence is not in itself a finding about the gene and the disease.
LGALS8 also shares sentences with these, for which no sentence is quoted: multiple sclerosis (5 papers); non-small cell lung carcinoma (5); breast tumor (3); Chagas disease (3); intrahepatic cholangiocarcinoma (3); parasite infection (3); prostate tumor (3); schizophrenia (3); atherosclerosis (2); head and neck carcinoma (2); head and neck squamous cell carcinoma (2); hepatocellular carcinoma (2); lymph node metastases (2); prostate adenocarcinoma (2); serous carcinoma (2); adenocarcinoma (1); ankylosing spondylitis (1); astrocytic tumor (1); autism spectrum disorder (1); benign prostatic hypertrophy (1); benign tumors (1); bipolar disorder (1); brain inflammation (1); carcinosarcoma (1); coronary artery disease (1); endometrioid ovarian cancer (1); erythroleukemia (1); fallopian tube carcinoma (1); glaucoma (1); hepatitis C (1).
A further 34 diseases each share a sentence with LGALS8 in 1 paper.